CD4 (CD4 molecule)
Diseases named in the same sentence as CD4 in open-access papers (continued):
Sharing a sentence is not in itself a finding about the gene and the disease.
infection (continued). "In the i.n. model, infection by vΔ169 caused enhanced production of several cytokines (IL-2, IL-6 and TNF-α) and chemokines (CCL11, CXCL9 and CXCL10) within 1 day p.i. and subsequent greater recruitment of macrophages and CD4+ and CD8+ T cells and increased lung weight." (PMID 26334635, 2015). "When compared with the data presented here, these studies indicate that the importance of ICOS signals in a CD4+ T‐cell response may be dictated by the route of antigen encounter, for example i.v. or i.n. infection with Lm‐2W1S results in very different memory cell responses." (PMID 25754933, 2015). "However, Env proteins from CSF samples containing compartmentalized viral lineages (all collected more than 4 months post infection) were significantly better at entering cells expressing low CD4 than Env proteins derived from equilibrated CSF samples (ANOVA; P<<0.001)." (PMID 25811757, 2015). "However, SIVcpz infection is associated with loss of CD4+ T-cells, and significant immune activation in the lymph node, and with changes in the structure of the secondary lymphoid environment." (PMID 26360709, 2015). "Thus, treatment of HIV+ FDC with sCD21-Ig prevents infection of healthy CD4 T cells in vitro." (PMID 26623655, 2015). "Additionally, in primary human CD4+ T cells we tested whether neutralizing TLR2 using 1 or 5 μg/mL TLR2-specific antibodies could inhibit infection." (PMID 26347747, 2015). "It is presently unclear whether compromised infection of myeloid lineage cells in vivo is responsible for this phenotype or if endogenous SAMHD1 must also be suppressed in memory CD4+ T lymphocytes, the cell lineage that sustains high levels of set-point viremia attending pathogenic infection." (PMID 25996507, 2015). "Finally, IDU showed the highest early mortality risk compared to PWA who acquired the infection through sexual contact; however, among IDU we observed the lowest proportion of individuals with a low CD4 cell count, suggesting that the elevated risk of early mortality was, in this group." (PMID 26067992, 2015). "Also, the proportion of CD4+CD25+Foxp3+ T cells among splenocyte population was highly elevated in recipients treated with ES L1 primed DCs similarly to the expansion of these cells during the muscle stage of the infection." (PMID 26114122, 2015). "Also, an increase of single-, double- and triple-cytokine-producing CD4+ T cells was observed in four (#6, #7, #8, #9) out of six animals after the secondary infection, supporting the assumption that multifunctional CD4+ T cells are a part of the FLUAVsw-specific memory-T-cell pool." (PMID 25971313, 2015). "The clusters of MHC-II+ cells and CD4+ T cells observed in schistosome-infected skin may represent how myeloid cells activate CD4+ T cells after S. mansoni infection, as suggested in other infection models." (PMID 25974019, 2015). "A further limitation is the cross-sectional nature of this study, where multiple time points or estimated time from infection would have been highly desirable to e. g. determine how the CD4/CD8 ratio could predict disease progression or mortality in this cohort." (PMID 26402620, 2015). "Thus, different infections elicit different CD4+ T cells producing IL-10." (PMID 26417443, 2015). "Since DC-mediated trans-infection of CD4+ T cells has been suggested as an important pathway of HIV-1 dissemination in vivo, significantly increased antibody titers might be necessary in vivo to achieve neutralization of IFN-α-DC or LPS-DC-mediated HIV-1 dissemination." (PMID 25760631, 2015). "However, untreated CD4+ T cells from splenic tissue—which expressed CD69 at levels comparable to those of CD4+ T cells isolated from tonsillar tissue—did show an increase in productive infection (1.8%) as compared to untreated CD4+ T cells from peripheral blood." (PMID 26067822, 2015).
infection (continued). "CD4+ T cells clonotypes with the highest affinity for antigenic pMHCII complexes will outcompete other lower-affinity clonotypes, but may be lost due to preferential infection in the case of T cell-tropic viruses." (PMID 26322045, 2015). "Whether those alterations, along with the maternal infection-related relative increase in CD8+ cells and relative decrease in CD4+ cells in the post-natal period that we report here, have a direct bearing on infants' immune response to infection remains an open question." (PMID 26580401, 2015). "The overall aim of this study was to determine whether the IPC, compared to Voluntary Counselling and Testing (VCT) services, was able to identify HIV positive individuals earlier in the clinical course of infection, defined by CD4 count and WHO clinical stage of HIV infection at first clinic visit." (PMID 25604750, 2015). "In these model systems effective immunity is dependent on robust CD4+ T-cell immune responses, the production of Th1-type cytokines such as interferon-γ (IFNγ), and “classical” activation of effector cells such as macrophages, leading to killing and clearance of infection." (PMID 25853653, 2015). "Thus, GITR on CD4 T cells may critically contribute to the initial viral set-point in infections such as HIV." (PMID 25590581, 2015). "However, despite the loss of CD4+ T-cells in SIVcpz infected animals in this study, SIVcpz infection shared features with the non-pathogenic infection of sooty mangabeys and African green monkeys with their species-specific viruses." (PMID 26360709, 2015). "Thus infectivity of MDMs is generally consistent with the conclusions derived from infection of Affinofile cells although the variability of infectivity of MDMs between donors precludes an accurate assessment of the range of CD4 entry phenotypes that can be observed using Affinofile cells." (PMID 25811757, 2015). "Therefore, HIV latency may be established by the direct infection of resting CD4+ T cells when they are exposed to soluble factors that do not induce classic T cell activation." (PMID 26067822, 2015). "Thus, we demonstrate that a number of CD4+ T cells with specificity to commensal antigens are present in naïve skin and we conclude that infection with schistosome cercariae enhances the exposure of CD4+ T cells to SC antigen resulting in the observed IL-10 production." (PMID 25974019, 2015). "Therefore, it is conceivable that deworming may exert a greater beneficial effect on CD4 count recovery in the setting of higher intensity STH infection." (PMID 25101890, 2014). "Regardless of whether “mode of infection” was added in the model (multivariate model I vs. model II), factors significantly associated with CD4 cell count changes included older age, subtypes (CRF01_AE and CRF08_BC), higher viral loads and no previous HAART." (PMID 25502811, 2014). "In addition, the removal of CD4+CD25+ Tregs significantly reduces the pathogen infection rate." (PMID 24944616, 2014). "Persistent levels of IFN I induce apoptosis in both HIV-infected CD4+ T cells and in those that do not become productively infected (bystander-killing) leading to accelerated depletion of CD4+ T cells during pathogenic infection." (PMID 25228901, 2014). "Also suggesting the negative regulation of the effector response, Albareda and cols reported that CD4+ T cells from patients with long-term chronic infection are primarily monofunctional, whereas in children in the early chronic stage of infection, multifunctional responses are also observed." (PMID 25104883, 2014). "Chronic immune activation may result from pathogenic events in the gut mucosa established during early infection, when viral replication in the intestinal mucosa results in massive killing of lamina propria (LP) CD4+ T cells, enteropathy, inflammation, and microbial translocation." (PMID 24495380, 2014).
infection (continued). "Surprisingly, high frequency of the predicted CXCR4-tropic viruses also existed in other CD4+T cell stratified groups, especially in CD4+T cell count≥500 (40.7% in algorithm I and 37% in algorithm II), similar to the observation among subtype D infection in Kenya’s study." (PMID 24586795, 2014). "During infection with S. mansoni, a strong Th2 response develops within the week following the initiation of egg production by mature female parasites and parasite eggs become trapped in the liver sinusoids and form focal points for intense CD4+ T cell dependent granulomatous inflammation." (PMID 25144366, 2014). "As protective CD8+ T-cells specific for a peptide of CSP from P. yoelii can be primed by dendritic cells (DCs) in lymph nodes after infection with sporozoites, it is likely that DCs in lymph nodes might also be critical for priming CD4+ T-cell responses to Plasmodium pre-erythrocytic stages." (PMID 25628621, 2014). "The finding suggests a mechanistic link between CD4+ T cell count and the virus replication rate, by indicating that HLA-B*5701 subjects with CD4+ T cell counts >750 cells/mm3 within the first 10–11 weeks of the infection will keep HIV-1 replication under better control during the subsequent years." (PMID 25187947, 2014). "Thus, DC-mediated CD4+ TEFF-cell activation in the dermis may be an essential component of the host defense that restricts infection to the skin epithelium and limits its spread after virus reemergence in sensory nerve endings." (PMID 25121482, 2014). "The early infection envelope viruses did not have significantly different replication AUC compared to the chronic infection envelope variants in the CD4+ T cells, both in aggregate (log AUC difference 0.3, 95% CI −1.1 – 1.6, p =0.6) or when the cells from different donors were analyzed separately." (PMID 25430652, 2014). "A detailed analysis of these rAd5-based trials showed a strong activation of Ad5-specific (but not HIV-specific) CD4 T cells in the gut mucosa of vaccinees, which may explain their enhanced susceptibility to infection, a finding reproduced in the monkey model." (PMID 25250026, 2014). "In a previous work we reported that the MHC class IB M1 haplotype correlated with a high viral load (P = 0.0280) and CD4 loss (P = 0.0343), whereas the MHC class IB M2 and M6 haplotypes correlated with increased susceptibility (P = 0.0199) and resistance (P = 0.0087) to infection, respectively." (PMID 25356594, 2014). "However such mice lack B cells or CD4+ T cells, and without CD4+ T cells MuHV-4 causes a lethal, chronic lytic infection even with a strong, polyclonal CTL response." (PMID 24967892, 2014). "However, some models proposed impractical assumptions, such as the assumption that all infections could be treated at a high CD4 count level or indeed at any level." (PMID 25580461, 2014). "Thus, we used similar methods to examine if envelope quasispecies from the 3 phases of infection had replication and binding differences in retinoic acid (RA) stimulated CD4+ and CD8+ T cells with flow cytometry confirmed high levels of α4β7 receptor respectively in the absence of any inhibitors." (PMID 25430652, 2014). "While TNFα-producing CD4+ T cells were not independently associated with future protection, the absence of cells producing this inflammatory cytokine was associated with the phenotype of asymptomatic infection." (PMID 24415936, 2014). "The relative MusPV1 E1∧E4 levels in the CD4 KO mice peaked at week 2 post-infection, showing 36-fold and 27-fold higher values than in wt and CD8-deficient C57BL/6 mice, respectively, gradually decreased thereafter and became undetectable at week 6 post infection." (PMID 25121947, 2014). "Thus we propose that the presence of CD4+ exosomes at the sites of infection could be detrimental to efficient viral spreading by reducing the population of disengaged/free viral particles." (PMID 25423108, 2014).
infection (continued). "Alternatively, CD4+ T cell activation might permit persistent low-level infection of these cells, in turn maintaining efficient stimulation of the HIV-specific immune response and thereby helping to control viral replication through inducing CD38−/HLA-DR+ profile." (PMID 25000587, 2014). "Having established that primary CD4+ T cells increase their glycolytic rate in response to infection with HIV-1, we sought to manipulate the metabolism of the cell to determine whether the glycolytic metabolism impacts on the fate of the infected cell and the viral replication cycle." (PMID 25421745, 2014). "Secondary infection with IAV revealed that these VLA-1+ cells represented 80% of the early producers of IFN-γ suggesting that the α1β1 integrin might be a marker of lung CD4 TRM cells." (PMID 25071787, 2014). "Indeed, CD4+ T-cells specific for pre-erythrocytic antigens have been documented, and in some cases, have been shown to correlate with protection in humans following natural infection and immunization." (PMID 25628621, 2014). "However, analysis of MusPV1 E1∧E4 spliced transcripts, as a measure of infection, at earlier time points revealed substantially higher numbers of MusPV1 E1∧E4 spliced transcripts relative to beta-actin in CD4 KO mice in the first three weeks post-infection, compared to wt C57BL/6 and CD8 KO mice." (PMID 25121947, 2014). "Furthermore, the resistance to T. cruzi infection of 5-LO−/− mice, in contrast to the susceptibility of WT mice, correlated with elevated numbers of splenic effector/memory T cells, including CD4+CD45RBlow and CD4+CD44high CD62Llow, at the end of the acute phase of infection." (PMID 25165415, 2014). "However, CD4 T cells can also contribute to immunosuppressive effects including IL-10 production which limits the induction of protective Th1 responses and promotes prolonged infection of the SG." (PMID 25120535, 2014). "Consequently, CD28-deficient mice have reduced expansion of effector CD4+ T cells and do not form T helper type 1 (Th1) and T follicular helper (Tfh) cells after infection or immunization." (PMID 25347065, 2014). "It is however worth referring that confocal imaging revealed the presence of some CxCR5+ PD1+ CD4 T cells inside B cell areas, at early time points after infection, suggesting that some bona fide Tfh cells might engage into the GC pathway, even though their numbers appear compromised." (PMID 24763747, 2014). "It includes predominantly healthy individuals with low mortality whose CD4 counts were measured at scheduled visits in contrast to other cohorts with an over-representation of ill individuals for whom CD4 count may be declining due to opportunistic illnesses or infections." (PMID 24831447, 2014). "Irf8-deficient mice, then, display defective Th1 responses (absence of antigen specific and IFNγ producing CD4+ T cells), enhanced Th17 responses, and are susceptible to in vivo infection with many intracellular pathogens including tuberculosis and blood-stage malaria." (PMID 23853600, 2013). "However, whether a defective IFN-γ secretion either by antigen-specific CD4+ T cells, or alternatively by NKT or CD8+ T cells underlies the susceptibility of Socs3fl/fl LysM cre mice to infection with M. tuberculosis remains to be determined." (PMID 23853585, 2013). "Moreover, the significant decrease of the bacterial load in the spleen from 8 days post-infection onwards of Brucella infection coincides with the presence of a large CD4+ CTLs population, a strong T cell response and a diminution of pro-inflammatory cytokine secretion." (PMID 24367519, 2013). "A repeat infection with Plasmodium parasites may induce CD4+ αβ T-cell exhaustion." (PMID 24009610, 2013). "However, in Chinese RM such low frequency of Th17 CD4 cells could be compensated by the emergence of NK T cells that express IL-17 early after infection." (PMID 23947613, 2013). "Thus, the nascent CD4+ T-cells from the transplant would be resistant to new infection." (PMID 23364195, 2013).
infection (continued). "Alternatively, there may be quantitative differences in the rates of differentiation of naïve CD4+ T cells into two subsets of effectors, differences in the rates of proliferation, death, and migration of different subsets of CD4+ T cells to the site of infection (population plasticity)." (PMID 23966946, 2013). "The CD4 Tcm, CD4 stem cells and Thpp cells have been proposed to act as a reservoir of memory cells with high proliferative potential and low effector function, that can give rise during subsequent infections to effectors with stronger effector functions but more limited proliferative capacity." (PMID 23526940, 2013). "However, additional evidence that such binding is important in trans infection is that it can be prevented by inhibitors that block the virus-cell fusion process, for example, CD4 attachment blockers (mAb), fusion blockers [T20], and chemokine receptor blockers (RANTES)." (PMID 24278768, 2013). "In addition it has been proposed that infection of immature CD4+/CD8+ ‘double positive’ thymocytes during thymopoiesis may generate a population of latently infected naïve T-cells." (PMID 23364195, 2013). "Moreover, a subset of CD14+ cells with low HLA-DR expression have recently been reclassified as myeloid-derived suppressor cells, and expand during infection or inflammation where they are capable of suppressing T cell responses and induce CD4+ CD25+ Foxp3+ regulatory T cells." (PMID 23446058, 2013). "bakeri infection leads to the atypical production of immunosuppressive TGF-β by intestinal CD4+ T cells in response to TLR-4 triggering by LPS poses the question whether such mechanisms of immune modulation help to avoid undesired immune activation by microbiota changes resulting from the infection." (PMID 24040152, 2013). "However, IL-7 signalling may additionally enhance integration of HIV-1 into the genome of target CD4 T cells as well as re-activation of productive infection from latently infected cells." (PMID 24321528, 2013). "The ability to use CCR5 coupled with low-to-absent CD4 levels is associated with enhanced macrophage infection and increased neutralization sensitivity, but the additional features of these Envs that may affect cell targeting is not known." (PMID 24219995, 2013). "Investigations exploring the role that distinct CD4+ T cell subsets may play in controlling T. cruzi infection are thus needed, particularly in non-susceptible models that control the infection more efficiently." (PMID 23776551, 2013). "Our studies show that Chlamydia-specific memory CD4 T cells persist for at least one year after infection, which may suggest the presence of persistent antigen and/or persistent Chlamydia without culturable Chlamydia organisms, after the clearance of infectious bacteria." (PMID 24204262, 2013). "Furthermore, infection of regulatory CD4+CD25+CCR4+ T cells might also determine the outcome of different immune responses in HTLV-I infection." (PMID 24470869, 2013). "We further examined whether the CD4-independent phenotype we observed during infection of cells over-expressing CCR5 also applied to primary cells, and whether the CD4-independent Envs were less efficient than CD4-dependent Envs in huCCR5 use in the context of primary cells." (PMID 24219995, 2013). "Thus, CD8+ T cells may provide a secondary line of defense when CD4+ T cell-activated macrophages fail to contain infection." (PMID 23805289, 2013). "Furthermore, our results suggest that SP-D, as we have previously shown for SP-A, may be a dual modulator of HIV infection by protecting CD4+ cells but enhancing the transfer of infection by dendritic cells in vivo." (PMID 23527085, 2013). "In our study inefficient mobilization of NK cells, CD4+ and CD8+ cells at the site of HSV-2 infection is accompanied by the increased virus titers observed in Fas and FasL deficient mice at day 3 and 7 of infection, indicating a possible delayed virus clearance from the vaginal tissue." (PMID 23922974, 2013).